BORCS7-ASMT (BORCS7-ASMT readthrough (NMD candidate))
Synonyms: formerly C10orf32-ASMT
Gene: Protein-coding gene on chromosome 10 (102,854,272 to 102,901,899, forward strand). Ensembl gene ENSG00000270316.
Genetic constraint (gnomAD): Missense variants: 106 observed, 102.52 expected, observed/expected ratio (o/e) 1.03, 90% interval 0.88 to 1.22. Synonymous variants: 48 observed, 37.21 expected, observed/expected ratio (o/e) 1.29, 90% interval 1.02 to 1.64.